TGFBR3 (transforming growth factor beta receptor 3)
Diseases named in the same sentence as TGFBR3 in open-access papers (continued):
Sharing a sentence is not in itself a finding about the gene and the disease.
adenocarcinoma (2 papers, 2017 to 2018). A common cancer characterized by the presence of malignant glandular cells. "Vasculogenesis-associated genes including NOTCH4 and TGFBR3 expression were significantly downregulated in adenocarcinoma tissue versus normal tissue (adjusted P values < 0.001 for both NOTCH4 and TGFBR3)." (PMID 29769567, 2018).
intestinal fistula (1 paper, 2017). "DCAF12 (rs10758242) and TGFBR3 (rs284148) showed modest associations with intestinal fistula development and intestinal stricture, respectively." (PMID 28045058, 2017).
TGFBR3 also shares sentences with these, for which no sentence is quoted: breast-invasive carcinoma (2 papers); Diabetes (2); diabetic nephropathy (2); head and neck cancer (2); hypospadias (2); Marfan syndrome (2); melanoma (2); multiple myeloma (2); Obesity (2); Primary Open Angle Glaucoma (2); schizophrenia (2); tongue squamous cell carcinoma (2); Alzheimer disease (1); attention deficit-hyperactivity disorder (1); benign tumors (1); breast (1); bronchopulmonary dysplasia (1); cardiovascular disease (1); cerebral infarction (1); cerebrovascular disease (1); chronic GVHD (1); chronic myeloid leukemia (1); cognitive decline (1); colon diseases (1); coronary artery disease (1); COVID-19 (1); Cyanosis (1); dengue (1); epithelial-myoepithelial carcinoma (1); exfoliation syndrome (1).
A further 34 diseases each share a sentence with TGFBR3 in 1 paper.